IL6 (interleukin 6)
Diseases named in the same sentence as IL6 in open-access papers (continued):
Sharing a sentence is not in itself a finding about the gene and the disease.
tumor (continued). "A Th2-polarized T cell response, characterized traditionally by the cytokine IL-4 but also TNF-α and IL-6, has been shown to support tumor growth." (PMID 26207636, 2015). "Dysregulated production of IL-6 and aberrant IL-6 activation pathways have been reported in many human cancers and play important roles in various tumor behaviors such as proliferation, migration and adhesion." (PMID 26501341, 2015). "In contrast to the IL-17 antitumor activity observed in mice injected with splenocytes, we observed that IFN-gamma, IL-6, IL-23, Ccl2, and Ccl20 proteins were significantly increased in tumor tissues of mice injected with IL-17." (PMID 26684834, 2015). "The results obtained allow us to infer that the EAT inoculation stimulated PGE2 production throughout its development and that the neoplasm growth has a positive influence on the production of IL-2 and IL-6 in the 13th day of tumor development." (PMID 26347589, 2015). "In the 1990s, there was increasing evidence that IL-6 contributes to metastasis and that serum IL-6 levels are adverse prognostic factors for the development of metastasis in several tumour types." (PMID 26508818, 2015). "Among inflammatory mediators, some cytokines and chemokins such as tumor necrosis factor (TNF), interleukin 1 (IL-1), interleukin 6 (IL-6), interleukin 8 (IL-8) are cytokines that play role in tumor genesis." (PMID 25948470, 2015). "DNA aneuploidy and association of the lesion with oncogenic viruses such as Epstain-Barr virus, Human Herpes virus type 8 and overexpression of IL-6 have also been demonstrated and proposed to be involved in the pathogenesis of the tumor by some investigators." (PMID 25945274, 2015). "In contrast, non-treated cells, showing low-level intrinsic expression of IL6, had only scattered cells at more distant tumor sites." (PMID 26215971, 2015). "Tumor-derived IL-6 is known to promote EC proliferation and new blood vessel generation that support the high metabolic demands of tumor cells." (PMID 26525581, 2015). "A limitation of the current study is that we did not have complete histories or demographic data to perform correlation studies to determine how IL-6 expression in DCIS relates to tumor prognosis." (PMID 26268945, 2015). "IL-6 blockade also restores the impaired ability of CD4+ T cells to promote CD8+ T-cell-dependent tumour elimination in aged mice, which requires IFN-γ." (PMID 25850032, 2015). "IL-1β induces IL-6 synthesis and release by T-lymphocytes, contributing to proinflammatory polarization of the tumor microenvironment a." (PMID 26131447, 2015). "In hepatic study, multifunctional cytokine IL-6 can stimulate hepatocyte proliferation and regeneration as well as growth modulation and tumor differentiation." (PMID 25908103, 2015). "It has been shown that these cytokines trigger proliferation of CSCs and enhance their invasive properties, whereas IL-6 mediates chemotaxis, which promotes MSCs homing to primary tumor growth sites in mouse xenograft models." (PMID 26694366, 2015). "Interaction of ADSCs and cancer cells stimulated secretion of IL-6 in ADSCs, which in turn acted in a paracrine manner on cancer cells to enhance their malignant properties, including tumor initiation (formation) and promotion (growth)." (PMID 25797257, 2015). "STAT3 is regarded as the main effector of IL-6 signaling and plays an important role in the survival and proliferation of tumor cells and immune cells." (PMID 26516076, 2015). "As to the B16 tumor challenge model, which is adopted in this study, existing reports have concluded that both IL-6 and IL-17A function as anti-tumor factors and can enhance the immune response." (PMID 25826372, 2015). "Proinflammatory cytokines, such as tumor necrosis factor alpha (TNFα) and interleukin-6 (IL-6), lead to an inflammatory state that stimulates tumor growth." (PMID 26347776, 2015).
tumor (continued). "For instance, neutrophil delivered TNFα, IL-6, and IL-17 were shown to promote tumor growth by modifying the function of stromal cells surrounding the tumor." (PMID 26648665, 2015). "CRP is synthesized in hepatocytes in response to cytokines, particularly IL-6, released from leucocytes within the tumor microenvironment." (PMID 26693355, 2015). "Several chemokines and growth factors released within the tumor microenvironment act as driving forces in this process by regulating Rho activity (e.g., IL-6, EGF)." (PMID 26053184, 2015). "In particular, IL-6 and IL-8 are important factors in predicting cell differentiation and growth of tumor cells." (PMID 26082902, 2015). "Both TNFα and IL-6 have been shown to promote tumour invasiveness and metastasis by secretion of matrix remodelling proteins matrix metalloproteinases." (PMID 25961014, 2015). "Elevation of serum IL-6 and IL-1β in tumor-bearing mice after docetaxel treatment implicates that docetaxel gives rise to side effects." (PMID 25797259, 2015). "Siltuximab, an anti-IL-6 monoclonal antibody, has demonstrated durable tumor and symptomatic responses in a multinational, randomized, placebo-controlled study of MCD." (PMID 26327301, 2015). "IL-6 has been shown to assist tumor progression though apoptosis inhibition, angiogenesis stimulation." (PMID 26198107, 2015). "Combination adjuvant MNP anti-IL6 siRNA and hepatic thermal ablation significantly reduced distant tumor proliferation (p = 0.045 vs. sham, p<0.001 vs. hepatic RFA alone)." (PMID 26154425, 2015). "High IL-6 levels are prognostic and correlate with tumour metastasis, disease stage, and short survival in several cancers including RCC." (PMID 25669986, 2015). "Using a limiting dilution xenograft assay, we also found that IL6 overexpression partially rescued the decrease in tumour-initiating activity of MCF-10A H-RasG12V cells induced by YAP/TAZ or SRF knockdown." (PMID 26671411, 2015). "Tumor-derived cytokines, such as GM-CSF, M-CSF, G-CSF, IL-6 and VEGF, initiate the first kind of signaling pathways that converge on activation of STAT3 and STAT5." (PMID 26285119, 2015). "We also showed that IL6 protein expressed by basal cancer cells activated other stromal cells (e.g., lymphatic endothelial cells) to promote tumor metastasis." (PMID 26173622, 2015). "Perhaps this cytokine is being produced by either neoplastic or late-phase response inflammatory cells as in animals with EAT the release of IL-6 from the 10th day of tumor growth is increased." (PMID 26347589, 2015). "Our experimental approach using conditional knockout mice presents more advantages than global mutants such as IL-6−/− in which the effect of changes in tumor growth cannot be attributed to a specific cell-type." (PMID 25741592, 2015). "Here, we found that IL-6 contributed to the protumor effects of ADSCs on tumor development in cancer cells by regulating genes that mediated tumor initiation and cell proliferation." (PMID 25797257, 2015). "In tumor-bearing state, the protumor potential of neutrophils is induced in bone marrow, which is mediated by G-CSF/IL-6." (PMID 25587026, 2014). "Our data showed that protumor neutrophils can be remodeled by IFN-γ and TNF-α, even in the presence of G-CSF/IL-6, resulting in the conversion of neutrophil function from tumor-promoting to tumor-suppressing." (PMID 25587026, 2014). "In turn, IL-6 acts in a paracrine manner increasing tumor gastric cell line proliferation through STAT3 signaling." (PMID 24978438, 2014). "IL-6 has been shown to be involved in tumor progression and metastasis through STAT3 signaling pathways." (PMID 24885636, 2014). "Expression of Ki67 in tumor cells and tumor microvessel density were lower in tumors vascularized with IL-6-silenced endothelial cells." (PMID 24533454, 2014). "Taken together, these data suggest that activation of the IL-6R, Syk, and JNK pathways are required for IL-6-induced AP-1 activation and tumor metastasis in human OSCC cells." (PMID 24398980, 2014).
tumor (continued). "We next investigated the effect of IL-6 expression on tumor growth and metastasis in vivo using xenograft experiments." (PMID 24789104, 2014). "Previous studies have indicated that the IL-6/ gp130/JAK signaling pathway can phosphorylate STAT3 Tyr705 in various tumor cells, including HCC." (PMID 24655440, 2014). "Giving different dosage of P2 toward HeLa cells, we also observed its modulation of the inflammatory response in tumor cells, controlling the release of interleukin-6 (IL-6) and tumor necrosis factor-alpha (TNF-α)." (PMID 24683359, 2014). "Our current study observed that both Enbrel and low-dose TNF-α pretreatments before IR markedly reduced the mRNA expressions of tumor promoting factors, IL-6 MMP-9 and E-selectin in IR liver." (PMID 24397824, 2014). "Tumor-secreted IL-6 has been reported to restores MDSC accumulation and is a downstream mediator of the IL-1β–induced expansion of MDSC." (PMID 25238263, 2014). "Along the same line, some tumor cytokines, including Interleukin-1 beta, tumor necrosis factor-alpha and interleukin-6, were found to be elevated in HCC patients, have been reported to block IGF-1 production in the liver." (PMID 24586785, 2014). "The IL-6 in the tumor microenvironment is known to induce resistance to anticancer agents in malignant diseases." (PMID 24675568, 2014). "Studies of STAT3-regulated expression of fascin will provide new insight into the mechanisms by which IL-6 promotes GC metastasis, in which multiple factors contribute to the critical step of primary tumor metastasis." (PMID 24527098, 2014). "In experimental and in vivo models, IL-6 increases the metastatic potential of circulating tumor cells and modulates tissue homeostasis in a target organ of metastasis such as the liver." (PMID 24886605, 2014). "For example G-CSF is known to cooperate with stem cell factor in haematopoiesis and IL-6 during bone marrow stem cell tumour progression." (PMID 24822049, 2014). "IL-6 is a cytokine that was initially recognized as a regulator of immune and inflammatory responses, but it also regulates the growth of many tumor cells, including prostrate carcinoma." (PMID 24658029, 2014). "Both SOMAmers prevented IL-6 signaling by blocking the interaction of IL-6 with its receptor and inhibited the proliferation of tumor cells in vitro as effectively as tocilizumab." (PMID 24415766, 2014). "The concentration of IL6 was dramatically higher in the co-culture system than in the mono-cultures, suggesting enhanced IL6 secretion in microenvironment including tumor and stromal cells." (PMID 24885802, 2014). "As in the tumor tissue, TGFβ upregulated IL-6 and, VEGF, and downregulated MCP1, CXCL1, and CXCL5 in cells with and without DNIIR expression." (PMID 25280532, 2014). "In serum of tumor-bearing mice on the other hand, interleukin-6 was elevated in all tumor models compared to tumor-free mice." (PMID 25401795, 2014). "We have previously demonstrated that a crosstalk initiated by endothelial cells enhances tumor cell survival and migration in vitro, and that endothelial cell-derived IL-6 induces phosphorylation of STAT3 in tumor cells." (PMID 24533454, 2014). "In this study, we have found that the expressions of NF-κB and IL-6 were synchronously increased in the tumor tissues and accompanied with the process of CAC in mice over the examined time-points." (PMID 25093140, 2014). "Of the myriad SASP factors associated with inflammation and malignancy, our data revealed that IL-6 is apparently specific for senescent MSCs to promote tumor progression." (PMID 25419563, 2014). "The relationships between HCMV, BMX, and IL-6 suggest a positive feedback loop in a signaling pathway leading to tumor cell proliferation and maintenance." (PMID 25549333, 2014). "Further examination discovered that elevated expression of IL-6 by the primary tumor was the likely culprit for this anti-tumor effect being limited to only metastatic disease." (PMID 24860789, 2014).
tumor (continued). "IL-6 neutralization attenuated tumor formation by MUC2 RNAi cells; it also increased CD8 T cell infiltration into the peritoneum." (PMID 25322805, 2014). "Consistently increased IL-6 levels in the VT-treated animals seems incoherent with previous reports of skin IR damage, where IL-6 is usually lowered in the group with less damage." (PMID 25159192, 2014). "Recently estrogen has been proven to exert protective effects against HCC through IL-6 restrictions, STAT3 inactivation and tumour-associated macrophage inhibition." (PMID 24708807, 2014). "In order to further address the relationship between overall macroscopic tumor number in the bowel and the densities of NF-κB and IL-6 in the tumor tissues, we performed correlation analyses." (PMID 25093140, 2014). "The recently identified heterodimeric member of the IL-6/IL-12 family of cytokines namely interleukin (IL)-27, has revealed potent anti-tumor effects in various tumor models and, importantly, freedom from toxicity in preclinical trials." (PMID 24681516, 2014). "Specifically, IL-6 triggers tumour cells to produce matrix metalloproteinase (MMP)-9 that promotes tumour growth by initiating angiogenesis." (PMID 24957270, 2014). "Among ER+ patients relativelly pro-inflammatori cytokines only the IL-6 was significantly higher in those who had a higher tumour size, nodal involvement (N+) and distant metastases (M+)." (PMID 25338520, 2014). "Interleukin-6 (IL-6) is a major cytokine that is known to affect immune response, which is expressed in tumor-infiltrating cells." (PMID 24984610, 2014). "IL-6 can induce tumorigenesis by hypermethylation of tumor suppressor genes as well as by hypomethylation of retrotransposon long interspersed nuclear element-1 (LINE-1) in oral squamous cell cancer lines in vitro, a frequent event in various human cancers." (PMID 24901008, 2014). "Because of the importance of cytokine control of the inflammatory microenvironment favoring or inhibiting tumor progression, we investigated the level of IL-6, IL-8 and MCP-1 released by Hep-2 cells." (PMID 25490767, 2014). "Koh and colleagues found that the expression of IL-6 in tumor tissues correlated with the concentration of serum IL-6, tumor progression, and the overall survival in NSCLC." (PMID 24789104, 2014). "The comparison between serum samples of tumor patients and the control group showed significantly elevated serum levels of osteopontin, IL-4 and IL-6." (PMID 25120668, 2014). "In tumor-bearing state, the capability of neutrophils to degranulate is attenuated due to the inhibitory effect of G-CSF/IL-6 on activation of PI3K and p38 MAPK pathways and the expression of Rab27a." (PMID 25587026, 2014). "Accordingly, a study with human cervical carcinoma lines showed that tumor-derived IL-6 and PGE2 were responsible for skewing monocyte differentiation toward a CD14+CD163+ M2-type phenotype, and that this was reversible upon co-incubation with Th1 cells." (PMID 24723924, 2014). "We then exposed tumor cells to IL-6 in the presence of chemical inhibitors of STAT3, Akt, or ERK pathways and analyzed the phosphorylation responses." (PMID 24533454, 2014). "Immunotherapy with lenalidomide enhanced activation of natural killer cells and inhibited their suppression by NB induced IL-6 or transforming growth factor-ß1 within the tumor environment." (PMID 24787299, 2014). "Both IL-6 and RANTES were associated with tumor progression, metastasis and macrophage activation in previous studies." (PMID 25322805, 2014). "Several in vitro and animal experiments using OSCC cells have shown that tumor cells produce several cytokines, including interleukin-6 (IL-6), IL-11, TNFα and parathyroid hormone-related protein (PTHrP)." (PMID 25373602, 2014). "HOXB9 promotes the secretion of angiogenic factors, including VEGF, to induce tumor proliferation through microenvironmental production of cytokines including IL6 signaling." (PMID 24885802, 2014).
tumor (continued). "Neither the pattern nor the amount of secreted cytokines, including paracrine growth factors like IL-6 that are known to shorten tumor latency in SCID mice, differed consistently among tumor-promoting and tumor-protective T cells (and data not shown)." (PMID 24853673, 2014). "Overexpression of NTPDase2 also contributes to increasing production of proinflammatory cytokines, IL-1β, TNF-α and IL-6, which intensify the progression and local invasion of tumour." (PMID 25530618, 2014). "A high level of serum IL-6 correlates with larger tumor size, elevated serum levels and liver metastasis." (PMID 25547486, 2014). "IL-6 is another typical proinflammatory cytokine with tumor growth effect, mainly by activating JAK tyrosine kinases and the transcription factor STAT3, as seen in lung, kidney, and breast cancer in which a high expression of STAT3 has been identified." (PMID 24901008, 2014). "Factors such as SDF-1, IL-8, IL-6 or MCP-1 which are released by HCC cells or by other tumor stroma components, have been described as chemoattractants for MSCs." (PMID 24736611, 2014). "STAT3 is activated through the IL-6 Pathway, which was also among the top 10 canonical pathways regulated by FoxO in response to tumor burden." (PMID 25539728, 2014). "Subsequently, we studied the effect of PD on HC+IL6 macrophages-induced tumor malignant transformation." (PMID 25313135, 2014). "Tumour associated macrophages or myeloid-derived suppressive cells, CD4+ Foxp3+ Treg cells and Th17 cells and their associated cytokines Il-6, TNF, IL-1β, IL-23 and TGF-β are generally recognized as dominant tumour-promoting forces." (PMID 24963981, 2014). "By secreting cytokines such as IL-6 and IL-10, HNSCC tumor cells promote a Th2-skewed response, which is associated with decreased antitumor efficacy." (PMID 24698959, 2014). "Both proteins, IL-1α and -β, have been implicated in tumor progression by inducing the expression of angiogenic and metastatic genes, cytokines and growth factors, such as MMPs, VEGF, IL-6 and 8, CCl2, CCL7, TNFα and TGFβ." (PMID 24887580, 2014). "In this study, IL-6 level in the tumor-draining lymph nodes of irradiated group was slightly induced compared to control." (PMID 25181290, 2014). "We have previously shown that Reg1 is strongly induced in antral tumours of gp130757FF mice coincident with IL-6 and IL-11 expression, and that haploinsufficiency of STAT3 results in reduced expression of Reg1, suggesting that it is a STAT3-regulated gene." (PMID 24804649, 2014). "Previous studies have found that several genes, including interleukin 6 and tumor necrosis factor-alpha, have opposite functions in normal and tumor cells." (PMID 24886599, 2014). "Here, we showed that specific blockade of the endothelial cell-tumor cell crosstalk (e.g. IL-6) is sufficient to inhibit tumor growth." (PMID 24533454, 2014). "Proinflammatory cytokines, i.e., IL-1β, TNF-α, IL-6 produced by tumor or host tissue due to tumor presence leads to both systemic and local inflammation in cancer." (PMID 25415607, 2014). "We then focused on the differences between the secretion of IL6 in monoculture and co-culture systems to elucidate the impact of microenvironment on tumor proliferation." (PMID 24885802, 2014). "Altogether, the increased expression of IL-1β and IL-6 together with proangiogenic effects of TP-expressing NSCLC on endothelium can contribute to tumor growth, implying TP as a target for antiangiogenesis in NSCLC." (PMID 24819505, 2014). "Th17 development was shown to be dependent on IL-1b/IL-6/IL-23 and NO production by MDSCs in both tumor-bearing mice and cancer patients." (PMID 25538892, 2014). "But our data suggest a possible role for microenvironmental IL6 in tumor cell proliferation, at least with regard to angiogenesis." (PMID 24885802, 2014).